TOB1 (transducer of ERBB2, 1)
Diseases named in the same sentence as TOB1 in open-access papers (continued):
Sharing a sentence is not in itself a finding about the gene and the disease.
gastric cancer (continued). "In conclusion, the present study demonstrates that Tob1 functions as a tumor suppressor protein in gastric cancer cells, at least in part, by inducing apoptosis and inhibiting proliferation, migration and invasion via the activation of Smad4- and suppression of β-catenin-mediated signaling pathways." (PMID 22710759, 2012). "Since Tob1 expression has been shown to be lost in human gastric carcinomas, we examined whether the restoration of Tob1 could prevent gastric cancer progression, and to elucidate the molecular mechanisms associated with its tumor suppressor function." (PMID 22710759, 2012). "We found differential expression of Tob1 in human gastric cancer (MKN28, AGS and MKN1) cells." (PMID 22710759, 2012). "We examined whether the decreased expression of β-catenin in Tob1-overexpressing gastric cancer cells could result from the reduced phosphorylation of Akt and GSK3β." (PMID 22710759, 2012). "Experimental data from our study indicated that TOB1 may induce autophagy in gastric cancer cells." (PMID 35186488, 2022). "Thus, our results provide new insights into TOB1-induced autophagy in gastric cancer." (PMID 35465266, 2022). "Therefore, this study evaluated whether and how the TOB1 gene induces autophagy in gastric cancer, aiming to provide more evidence for TOB1 as a potential therapeutic target in gastric cancer." (PMID 35186488, 2022). "In addition, we speculated that differentially expressed miRNAs in the exosomal content were taken up by the receptor cells, which might affect the activity of PI3K/Akt/mTOR pathway, and then induce autophagy in gastric cancer cells with TOB1 gene knockout." (PMID 35465266, 2022). "Thus, it would be worthwhile to investigate whether the decreased phosphorylation of Akt and the reduced expression of β-catenin upon overexpression of Tob1 in gastric cancer cells also results from the induction of PTEN." (PMID 22710759, 2012). "However, the role of Tob1 in gastric cancer progression and its underlying mechanisms have not been fully clarified." (PMID 22710759, 2012). "Thus, the restoration of Tob1 in gastric cancer patients could delay the disease progression and improve the prognosis by inhibiting migration and invasion of cancer cells." (PMID 22710759, 2012). "We previously confirmed that transducer of ERBB2, 1 (TOB1) gene, can induce autophagy in gastric cancer cells." (PMID 35465266, 2022). "We previously observed down-regulation and phosphorylation of TOB1 in gastric cancer (GC)." (PMID 29088861, 2017). "In previous results, we found a trend of lower TOB1 expression in neutrophils of gastric cancer tissue compared to adjacent non-cancerous tissue." (PMID 38617839, 2024). "LC3 puncta were observed in gastric cancer cells 48 h after TOB1 lentivirus transduction, and no clear LC3 puncta formed in gastric cancer cells transduced with the control lentivirus." (PMID 35186488, 2022). "Moreover, in vitro miR25 overexpression promotes gastric cancer progression by downregulating transducer of ERBB2, 1 (TOB1) expression; consistently, patients with gastric cancer with high concentrations of miR25, in circulation, displayed poor survival." (PMID 26262875, 2015). "In addition, we found a novel mechanism showing that Tob1 induced PARP cleavage by promoting caspase-3 activity, leading to the apoptosis of gastric cancer cells." (PMID 22710759, 2012). "Differential ultracentrifugation was used to extracted the exosomes from the culture medium of gastric cancer cell line AGS-TOB1 ectopically overexpressing TOB1 (exo-AGS-TOB1, experimental group) and AGS-empty-vector cell line with low expression of endogenous TOB1 (exo-AGS-Vector, control group)." (PMID 35465266, 2022). "Thus, the induction of Smad4 expression by Tob1 in MKN28 and AGS cells could inhibit gastric cancer progression through activation of Smad4-mediated signaling." (PMID 22710759, 2012).
gastric cancer (continued). "However, the expression and the activity of MMP-2/-9 in gastric cancer cells remained unaffected by Tob1 overexpression (data not shown)." (PMID 22710759, 2012). "Moreover, correlation analysis showed that TOB1 was positively correlated with the expression of ATG3 and ATG7 in gastric cancer but not in normal gastric tissue." (PMID 35186488, 2022). "The expression level of TOB1 was positively correlated with the expression levels of ATG3 (R = 0.32, ***P = 2 × e−11) and ATG7 (R = 0.23, ***P = 1.7 × e−06) in gastric cancer tissues but not in normal gastric tissue (ATG3, R = 0.027, P = 0.7; ATG7, R = 0.033, P = 0.64)." (PMID 35186488, 2022).
breast carcinoma (13 papers, 2011 to 2025). "All these results highly suggest that the loss of TOB1 expression plays a vital role in breast cancer progression." (PMID 26694352, 2015). "TOB1 expression levels are inversely associated with the tumorigenicity and metastatic ability of breast cancer cell lines as well as with tumor progression in patients with breast cancers." (PMID 36849756, 2023). "Furthermore TOB1 has previously been associated with poor distant metastasis free survival in breast cancer patients." (PMID 26807845, 2016). "Interestingly, one of these genes was TOB1 (Transducer of ErbB2 1), which has been recently implicated in breast cancer metastasis." (PMID 21999641, 2011). "Furthermore, TOB1 expression levels are inversely associated with the tumorigenicity and metastatic ability of breast cancer cell lines as well as with tumor progression in patients with breast cancers." (PMID 26694352, 2015). "Previous findings have indicated that the transducer of ERBB2, 1 (Tob1) gene expression is downregulated in various cancers including breast cancer." (PMID 40918450, 2025). "In general, the Tob1 is downregulated in breast cancer cells compared with normal cells, and the miR-25-3p knockdown can repress the proliferation of breast cancer cells by upregulating Tob1 expression." (PMID 40918450, 2025). "PTEN is known to interact with TOB1 in lung and breast cancer 17, 34-35, and our immunoprecipitation results confirmed this interaction in SGC-7901 and AGS cells." (PMID 35154457, 2022). "Overexpression of TOB1 enhances the apoptosis rate of breast cancer cells by regulation of the JNK and p38 pathways, and it enhances cell cycle arrest and radiosensitivity." (PMID 35154457, 2022). "One study found that TOB1 was involved in the regulation of chemotherapeutic sensitivity in HER2‐positive breast cancers, suggesting that TOB1 plays different roles in different molecular subtypes of cancer." (PMID 31891232, 2020). "In survival analyses based on Kaplan-Meier Plotter, TOB1, BTG1 and BTG4 showed significant associations with survival outcome of different subtypes of breast cancer." (PMID 28922388, 2017). "In contrast to multiple lines of evidence supporting the tumor suppressor function of TOB1, a recent study uncovered another role of TOB1 in promoting proliferation of estrogen-independent breast cancer cells." (PMID 26694352, 2015). "Adenoviral-mediated overexpression of TOB1 sensitizes breast cancer cells to radiotherapy and induced apoptosis by preventing DNA repair and inducing the expression of the pro-apoptotic protein BAX." (PMID 26694352, 2015). "Microarray analysis of 25 human tumors with primary breast cancers and subsequent biochemical analysis revealed that, in most of the breast cancers and lymph nodes, expression levels of TOB1 mRNA and protein are altered." (PMID 26694352, 2015). "While the loss of Tob1 has been implicated in the progression of human papillary thyroid carcinomas, ectopic expression of Tob1 inhibited cell cycle progression and reduced the growth of human breast cancer cell xenografts in nude mice." (PMID 22710759, 2012). "Similar effects of Tob1 on Bax and Bcl-2 expression in human breast cancer cells have been reported earlier." (PMID 22710759, 2012). "TOB1 is regulated by EGF-Dependent HER2 and EGFR signaling and TOB1 protein expression and phosphorylation is associated with EGF-dependent erbB signaling and proliferation in breast cancer." (PMID 27506935, 2016). "In breast cancer cells, Tob1 overexpression could induce the apoptosis of cancer cells." (PMID 40918450, 2025). "The following genes were reported to be lower expressed in breast cancer samples of cases compared to controls in two different studies but were reported to be higher expressed in another study: PABPC1, ARPC1A, TXN, TOB1." (PMID 36627894, 2022).
lung carcinoma (7 papers, 2011 to 2021). "The loss of heterozygosity (LOH) of TOB1 mapped on chromosome 17q is also common in human lung cancer tissue." (PMID 26694352, 2015). "Loss of TOB1 expression promoted lung cancer cell proliferation, invasion, and metastasis." (PMID 29088861, 2017). "With regard to genes negatively associated with SLC2A5, a previous study showed that overexpression of TOB1 significantly inhibited the proliferation and metastasis of lung cancer cells." (PMID 34604392, 2021). "According to this study, elevated expression of phosphorylated TOB1 (at serine 152 and serine 154 residues), an inactive form of the protein, was only observed in lung cancer tissues compared to adjacent normal tissues." (PMID 26694352, 2015). "Immunohistochemical analysis of human lung cancer tissues revealed decreased expression of TOB1 in 72% of patients with squamous cell carcinoma." (PMID 26694352, 2015). "A recent study demonstrated that overexpression of Tob1 in lung cancer cells increased the expression of another tumor suppressor protein phosphatase and tensin homolog (PTEN), which is a negative regulator of Akt." (PMID 22710759, 2012). "TOB1 could inhibit the proliferation and metastasis of lung cancer cells through a series of downstream regulators, including cyclin D1, AKT signal transduction, BCL-2, BCL-XL, and SMAD4." (PMID 34604392, 2021). "Moreover, decreased TOB1 expression in lung cancer (72%, 31/43), and altered TOB1 phosphorylation in lung adenocarcinoma (76%, 16/21) was shown to be an early event (stage I, 78%, 18/23), even in subjects with bronchial dysplasia (100%, 5/5)." (PMID 29088861, 2017).
colon cancer (4 papers, 2011 to 2023). "Our findings provide important insights into a previously unrecognized oncogenic role of Tob1 in colon cancer and suggest that Tob1 is an adverse prognostic factor and therapeutic target for colon cancer." (PMID 30447686, 2018). "Here, we reveal a unique oncogenic role of Tob1 in colon cancer." (PMID 30447686, 2018). "Tob1 expression was upregulated during colon cancer progression, was significantly correlated with tumour size and tumour differentiation, and was a prognostic indicator of colon cancer." (PMID 30447686, 2018). "However, it has been also reported that Tob1 expression may be upregulated during the progression of colon cancer, which is significantly correlated with tumor size and a prognostic indicator, such as survival rate in colon cancer." (PMID 36230852, 2022).
experimental autoimmune encephalomyelitis (4 papers, 2014 to 2022). An autoimmune demyelinating disease of the central nervous system that is produced experimentally in animals by the injection of homogenized brain or spinal cord in Freund's adjuvant. "Recently, TOB1 has been implicated in several autoimmune diseases, including multiple sclerosis and experimental autoimmune encephalomyelitis (EAE)." (PMID 36085336, 2022). "Subsequently the same group also showed that TOB1−/− mice exhibited exacerbated symptoms of experimental autoimmune encephalomyelitis (EAE), suggesting that TOB1 has an important role in constraining CNS autoimmunity." (PMID 27386265, 2016). "Consistently, Tob1 ablation in mice exacerbates the clinical phenotype of the MS model experimental autoimmune encephalomyelitis (EAE)." (PMID 27546286, 2016). "Subsequent studies employing Tob1-knockout mice confirmed that the absence of Tob1 in the experimental autoimmune encephalomyelitis (EAE) paradigm was associated with increased inflammation, infiltrating T cells and myelin-reactive Th1 and Th17 cells." (PMID 27546286, 2016).
papillary thyroid cancer (4 papers, 2012 to 2020). "The levels of TOB1 phosphorylation in papillary thyroid cancer are directly associated with tumor size, metastasis, and the presence of poorly differentiated lesions." (PMID 26694352, 2015). "The level of p-TOB1, which was directly linked to tumor size, lymph node metastasis, extra thyroid extension, and the presence of poorly differentiated lesions, was shown to promote progression of papillary carcinoma, particularly in the later phase." (PMID 29088861, 2017). "The phosphorylation-mediated inactivation of TOB1 is more frequent in papillary thyroid carcinoma than that in follicular thyroid carcinoma." (PMID 26694352, 2015).
viral infection (4 papers, 2022 to 2024). "Notably, the significant increase in ISGs caused by TOB1 deficiency is the main factor in inhibiting viral infection in IBRS-2 cells, while TOB1 deletion inhibiting FMDV infection via the EGFR pathway, is common in IBRS-2, PK-15, and iPAM cells." (PMID 38512977, 2024). "Previous research has indicated that following viral infection, TOB1 dampens antiviral immune responses of macrophages by mediating IFN-β expression." (PMID 38617839, 2024). "To investigate the role of TOB1 in viral infection, we used transcriptome sequencing to identify significantly differentially expressed genes between control and TOB1-knockout IBRS-2 cells." (PMID 38512977, 2024). "In this study, we demonstrated that viral infection induced the interaction of the transducer of ERBB2.1 (TOB1) with IRF3, which bound to the promoter region of Ifnb1 in macrophages." (PMID 36085336, 2022). "Next, we investigated the physiological and pathological relevance of TOB1 in the context of viral infection in vivo." (PMID 36085336, 2022). "In this study, we demonstrated that TOB1, which is induced during viral infection, inhibited IRF3-directed IFN responses and antiviral immunity." (PMID 36085336, 2022). "In the present study, we determined that viral infection markedly induced the interaction of TOB1 with IRF3, which is bound to the promoter region of Ifnb1 in macrophages." (PMID 36085336, 2022). "We found that viral infection-induced TOB1 interacted with IRF3 and bound to the promoter region of Ifnb1, leading to recruitment of HDAC8 and suppression of IFN-β production." (PMID 36085336, 2022). "DEGs such as cytosolic carboxypeptidase 3, dual-specificity protein phosphatase 10, 15, dynein axonemal heavy chain 17, fasciclin 2, inhibin beta chain, replication factor A protein 1, and Tob1 were found enriched and favored the virus infection and circulation in B. tabaci." (PMID 35572639, 2022). "Furthermore, immunofluorescence assays showed that TOB1 interacted with IRF3 in the cytoplasm of resting mouse embryonic fibroblasts (MEFs), and viral infection further enhanced the interaction and promoted TOB1 and IRF3 translocation to the nucleus." (PMID 36085336, 2022).
autoimmune disease (3 papers, 2014 to 2022). A disorder resulting from loss of function or tissue destruction of an organ or multiple organs, arising from humoral or cellular immune responses of the individual to their own tissue constituents. "Further studies are needed to assess the potential for selective modulation of Nfatc2, Tob1, or both as part of therapeutic strategies seeking to alter T cell responses in patients with autoimmune diseases and cancer." (PMID 24945807, 2014). "Given the important roles of type I IFNs in multiple autoimmune disorders, TOB1 may play an essential role in the development of autoimmune diseases caused by aberrant IFN responses." (PMID 36085336, 2022).
colorectal cancer (3 papers, 2021 to 2025). A primary or metastatic malignant neoplasm that affects the colon or rectum. "TOB1 is negatively regulated by miR-32-5p to regulate radiosensitivity and inhibit the metastasis and invasion of colorectal cancer cells." (PMID 35154457, 2022). "In two recent reports, miR-32 was shown to promote tumorigenesis, radioresistance, migration, and invasion of colorectal cancer by targeting BMP5 and TOB1." (PMID 34938324, 2021).
gastric tumor (3 papers, 2012 to 2024). "TOB1 is expressed in the cytoplasm and/or nucleus of gastric tumor cells, and its main anti-proliferative function is exerted in the nucleus." (PMID 38617839, 2024). "Alternatively, gastric tumor cells overexpressing TOB1 induce autophagy through the secretion of exosomes." (PMID 38617839, 2024). "Therefore, the mechanism by which inactivation (no phosphorylation) of the AKT (Ser473)/mTOR (Ser2448) pathway affects TOB1-induced autophagy in gastric tumor cells needs to be further explored." (PMID 35186488, 2022).
lymph node metastasis (3 papers, 2017 to 2022). "We found that decreased nuclear TOB1 was positively correlated with lymph node metastasis, distant metastasis, and TNM stage, but that increased nuclear p-TOB1 was correlated with differentiation grade, depth of invasion, and TNM stage." (PMID 29088861, 2017). "Nuclear TOB1 expression was reduced in GC patients with lymph node metastasis (N0 vs. ≥ N1, P = 0.008), distant metastasis (M0 vs. M1, P = 0.007), and high TNM stage (I and II vs. III and IV, P = 0.043)." (PMID 29088861, 2017).
multiple sclerosis (3 papers, 2021 to 2023). A progressive autoimmune disorder affecting the central nervous system resulting in demyelination. "In fact, Tob1 downregulation has been associated with a higher severity of disease in patients with multiple sclerosis." (PMID 33730591, 2021). "TOB1, which codes for an antiproliferative protein that targets mRNA deadenylation and decay, has previously been associated with neurodegenerative disorders, such as multiple sclerosis and a TOB1 deletion has been associated with hippocampus-mediated acute stress response in animal models." (PMID 36959830, 2023). "Tob1 deficiency (or downregulation) in patients with clinically isolated syndromes at risk of conversion to clinically definite multiple sclerosis may contribute to the differentiation and proliferation of proinflammatory T-cells and central nervous system autoimmunity." (PMID 36085336, 2022).
rheumatoid arthritis (3 papers, 2021 to 2024). A chronic, systemic autoimmune disorder characterized by inflammation in the synovial membranes and articular surfaces. "In addition, exosomal miRNA-486-5p derived from rheumatoid arthritis fibroblast-like synoviocytes (RA-FLSs) induces osteoblast differentiation through the Tob1/BMP/Smad pathway, contributing to the pathogenesis of RA." (PMID 39372407, 2024). "A recent study found that exosomal miRNA-486-5p derived from rheumatoid arthritis fibroblast-like synoviocytes may induce osteoblast differentiation through the Tob1/BMP/Smad pathway." (PMID 33977502, 2021). "As has been reported, TOB1 downregulation can radically induce ALP activity and OSX expression in rheumatoid arthritis." (PMID 37268992, 2023).
thyroid cancer (3 papers, 2012 to 2023). "In clinical samples of patients with breast and thyroid cancer, decreased TOB1 is frequently detected, as well as BTG2 is reduced in breast and kidney cancer." (PMID 28922388, 2017). "Moreover, inactive, phosphorylated TOB1 is frequently found in clinical samples of patients affected by lung and thyroid cancer." (PMID 23236473, 2012).